MIR302A (microRNA 302a)
Synonyms: hsa-mir-302; hsa-mir-302a; MIRN302; MIRN302A; mir-302a
Gene: MicroRNA gene on chromosome 4 (112,648,183 to 112,648,251, reverse strand). Ensembl gene ENSG00000207927.
Pathways (Reactome):
Signal Transduction: Pre-NOTCH Transcription and Translation
Gene Ontology:
Biological process: miRNA-mediated post-transcriptional gene silencing
Cellular component: RISC complex
Homologues: Orthologues: chimpanzee ptr-mir-302a (100% identical), macaque mml-mir-302a (100% identical), rabbit MIR302A (99% identical), dog MIR302A (96% identical), guinea pig MIR302A (88% identical), tropical clawed frog xtr-mir-302 (70% identical). Paralogues in human: MIR302D (75% identical), MIR302B (72% identical), MIR302C (70% identical).
Diseases named in the same sentence as MIR302A in open-access papers:
MIR302A is named in the same sentence as 2 diseases in open-access papers, as found by Europe PMC text mining. Sharing a sentence is not in itself a finding about the gene and the disease. The quoted sentences say what the papers report.
colorectal cancer (1 paper, 2021). A primary or metastatic malignant neoplasm that affects the colon or rectum. "In turn, the CN regions contained three known microRNAs (MIR34A, MIR367 and MIR302A) that regulate the expression of genes involved in the pathogenesis of colorectal cancer." (PMID 34202891, 2021).
MIR302A also shares sentences with these, for which no sentence is quoted: lung carcinoma (1 paper).